LAMA2 (laminin subunit alpha 2)
Diseases named in the same sentence as LAMA2 in open-access papers (continued):
Sharing a sentence is not in itself a finding about the gene and the disease.
tumor (38 papers, 2014 to 2025). "LAMA2, encoding a subunit of laminin protein, has been identified as a tumor suppressor in a recent genomic study and LAMC3 is another member of this gene family." (PMID 31722693, 2019). "Furthermore, a significant positive correlation was observed between core genes, such as HPIPR and LAMA2, within the high-risk group and various pro-tumor pathway genes." (PMID 40589759, 2025). "Germline loss of chromosome 6q22.33, which harbors two potential tumor suppressor genes, PTPRK and LAMA2, was also identified; this may increase tumor predisposition further." (PMID 26432421, 2015). "LINC01270 inhibits the expression of LAMA2 to enhance the proliferation, invasion and metastasis of tumor cells, and reduces their apoptosis rate." (PMID 37901333, 2023). "On the contrary, the authors suggested the overexpression and demethylation of LAMA2 to suppress tumor cell invasion via the PTEN-PI3K/AKT signaling pathway and MMP-9 inhibition." (PMID 37958702, 2023). "We found that the expression level of LAMA2, TIMP4, and TMTC1 was higher in all TCGA tumours and significantly associated with poor survival." (PMID 37238942, 2023). "High expression levels of LAMA2 in the microenvironment are observed to be inversely correlated with tumor purity and positively related to immune cells." (PMID 35954405, 2022). "Abnormal methylation at the target CpG sites of Laminin α2 (LAMA2) was observed at a high frequency in CRC tumor tissues and less frequently in normal tissues adjacent to the tumor, revealing that it is also a potential biomarker." (PMID 34502094, 2021). "Lama2 is a tumor suppressor by changes in its expression and methylation patterns and can modulate PTEN to exert effects on PI3K/AKT signaling." (PMID 34764977, 2021). "In human samples, LAMA2 expression was barely detectable in both non-tumor and PDAC specimens." (PMID 39811640, 2025). "As we can see, LAMA2 expression was significantly lower in tumor tissues than in normal tissues." (PMID 37872487, 2023). "We subsequently verified the expression by western blotting assay on both tumor and normal tissues and could see that LAMA2 expression was significantly lower in tumor tissues than in normal tissues." (PMID 37872487, 2023). "However, seldom researchers paid attention to the direct correlation between LAMA2 overexpression and tumor progression." (PMID 36357874, 2022). "Similarly, laminins were predominantly downregulated across tumour sample groups among which LAMA2 and LAMA3 were downregulated across all sample groups." (PMID 36220861, 2022). "Previous studies found that a decrease in Lama2 expression was accompanied by an increase in DNA methylation near the transcription start site; promoter DNA methylation and downregulation across multiple cancer types indicate that Lama2 is a tumor suppressor gene." (PMID 34305583, 2021). "Likewise, the following marker genes were selected for analysis in PF tumours: LAMA2, ALDH1L1, SLC6A13, IGSF1, and CXorf67 for PFA; and NELL2, DNAH1, CEP83, C9orf72, and NXNL2 for PFB tumours." (PMID 34314101, 2021). "We found LUAD tissue expressed lower LAMA2 expression than para-tumor tissue." (PMID 32792503, 2020). "Moreover, patients with low LAMA2 expression were 30% more likely to have tumor recurrence (odds ratio = 1.7, P = 0.034, Chi-Square test)." (PMID 25159915, 2014). "Thus, the role of LAMA2 in tumor immune cell infiltration urgently needs to be verified." (PMID 35954405, 2022). "We thought the function of LAMA2 may be tumor specific or dependent on the stage of oncogenesis." (PMID 32792503, 2020). "LAMA2, MAP1B, and HIP1R were among the genes with higher mutation frequencies (8%, 6%, and 5%, respectively), suggesting these mutations play a crucial part in tumor initiation and progression, and these genes could be potential driver genes or therapeutic targets." (PMID 40589759, 2025). "Therefore, the function of LAMA2 may be tumor-specific or dependent on the stage of oncogenesis." (PMID 37519798, 2023).
tumor (continued). "The smaller cluster (14.2% of tumours) showed high expression of five genes belonging to the PFB signature and NELL2+/LAMA2− expression pattern." (PMID 34314101, 2021). "The third cluster included 18 tumours that showed expression of both NELL2 and LAMA2 (NELL2+/LAMA2+)." (PMID 34314101, 2021). "The MBEN tumor microanatomy is visible in the H&E staining, and its structure was highlighted by all iST methods at the transcript level, with the transcription of NRXN3 and LAMA2 as marker genes for the nodular and internodular compartments, respectively." (PMID 40542418, 2025). "However, the Visium analysis did not offer sufficient spatial resolution to distinctly delineate the two tumor compartments, as indicated by the NRXN3/LAMA2 expression ratio." (PMID 40542418, 2025). "We found that the expression level of LAMA2, TIMP4, and TMTC1 was higher in all TCGA tumours." (PMID 37238942, 2023). "Expression levels of LAMA2, TIMP4, and TMTC1 across TCGA tumours are shown in." (PMID 37238942, 2023). "The ROC analysis of the laminins in OC datasets showed that the LAMA2/A4/A5, LAMB1/B2/B3, and LAMC2 mRNA levels could be considered to effectively differentiate between malignant tumor and non-tumor tissues." (PMID 34512203, 2021). "The first showed seven tumours with expression of NELL2 but not LAMA2 (NELL2+/LAMA2−), which overlapped exactly with tumours from the PFB cluster." (PMID 34314101, 2021). "What’s more, lower expression levels of LAMA2 predict poor survival and higher chance of cancer recurrence in HCC patients, suggesting an important role of the extracellular matrix and cell adhesion in tumor progression of a subgroup of HCC patients." (PMID 32792503, 2020). "In our study an increased expression of LAMA2 indicated for a better overall survival rate of the patients without significant connection with tumor grade." (PMID 27390862, 2016). "In addition, all detected laminins were down-regulated in tumour samples compared to matched non-tumour samples, from 1.8-fold for laminin α2 chain (LAMA2) to 18.6-fold for laminin α3 chain (LAMA3)." (PMID 37397358, 2023). "The second cluster included 23 tumours showing expression of LAMA2 but not NELL2 (NELL2−/LAMA2+)." (PMID 34314101, 2021). "In addition, unlike DMD and LAMA2 which were deleted, only missense mutations were seen in TTN, as has been reported in a number of other tumor types and is not unexpected given the large size of the TTN gene." (PMID 30575736, 2018). "Lower expression levels of LAMA2 correlate with a proliferative signature, and predict poor survival and higher chance of cancer recurrence in HCC patients, suggesting an important role of the extracellular matrix and cell adhesion in tumor progression of a subgroup of HCC patients." (PMID 25159915, 2014). "It is conceivable that functional LAMA2 in the extracellular matrix may keep the proliferation of regenerating hepatocytes in check, and defective or lack of LAMA2 facilitates tumor progression." (PMID 25159915, 2014). "Notably, in H1 ESCs the REST binding patterns at all of these genes (except LAMA2) matched with those in the tumor cell lines, suggesting that REST regulation of these genes may have a role in cell proliferation, since active growth is a common feature of ESCs and tumor cells." (PMID 24922058, 2014). "Overall, the ROC analysis of the laminins in the OC sets indicated that LAMA2/A4/A5, LAMB1/B2/B3, and LAMC2 could be considered to accurately differentiate between tumor and non-tumor tissues." (PMID 34512203, 2021).
cancer (32 papers, 2013 to 2026). A tumor composed of atypical neoplastic, often pleomorphic cells that invade other tissues. "Recurrent insertions were located near cancer-associated genes, including RB1, NEDD4, FTO, LAMA2, NOD1, and KCNB2, implicating LINE-1 activity in cis-regulatory remodeling of oncogenic pathways." (PMID 41681929, 2026). "It was found that the knockdown of LAMA2 promoted cancer cell migration, invasion, epithelial-mesenchymal transition (EMT), and activation of the PI3K/AKT pathway." (PMID 37872487, 2023). "A decrease in LAMA2 gene expression level is observed in some types of cancer and is a predictor of poor survival of cancer patients." (PMID 36362280, 2022). "We identified several extracellular proteins as up‐regulated in invaded compared to noninvaded nerves (some of these were also seen in PNI compared to non‐PNI cancer), including laminins LAMA2, LAMB1, COL6A3, periostin (POST), nidogen 1 (NID1), and TNC." (PMID 30690892, 2019). "miR-29 family plays a dominant role in regulating extracellular matrix genes, such as collagens, LAMA2, integrin β, Mmp2, fibrillin, secreted protein, acidic, and Sparc, consequently contributing to the promotion of cancer cell migration and metastasis." (PMID 25889078, 2015). "LAMA2 stimulation led to reduced cancer cell invasion, migration, proliferation, and would healing." (PMID 39811640, 2025). "Decreased expression of LAMA2 has been reported in various cancers." (PMID 37238942, 2023). "In addition, we examined multiple cancer cell lines and found that a decrease in LAMA2 expression was accompanied by an increase in DNA methylation near the transcription start site." (PMID 25159915, 2014). "DNA methylation at the LAMA2 promoter region found by us and others suggests that epigenetic mechanisms may target LAMA2 in multiple cancers." (PMID 25159915, 2014). "Studies on LAMA2 and RAPGEF3 have identified their role in cancer progression, through the regulation of signaling pathways." (PMID 39180549, 2024). "Compared with paracancerous tissues, AKAP7, EFEMP1, EPN2 and LAMA2 were lowly expressed in cancer tissues, while RPS6KA1, SLC1A6, TRABD and ZNRD1 were highly expressed in cancer tissues." (PMID 37123010, 2023). "In this study, EFEMP1, LAMA2 and SLC1A6 were differentially expressed not only in N0 and N1–N3 groups, but also in cancer and paracancerous groups." (PMID 37123010, 2023). "EGFR, IGF1R, LAMA2, MYLK, PIK3CA, PIK3R1, and MYLK are members of the focal adhesion pathway, whose dynamics are highly altered in cancer cells." (PMID 31024613, 2019). "Among these, LAMA2, DUSP1, PRKAR1B, and APP were downregulated while the rest of the genes were upregulated in cancer as compared to normal cervical samples in the samples used for microarray." (PMID 24403257, 2013). "In co-culture experiments, we found that Lama2 expression in wild-type fibroblasts was 7.3% down-regulated 72 h after co-culture with KPC cancer cells, compared to the expression without co-culture with KPC cancer cells." (PMID 39811640, 2025). "These four pathways were proteoglycans in cancer (ANK2, FASLG, HSPG2, PTPN11, STAT3, and VEGFA), HIF-1 signaling (ARNT, STAT3, and VEGFA), FoxO signaling (FASLG, SMAD4, and STAT3), and ECM-receptor interaction (HSPG2 and LAMA2)." (PMID 29300322, 2018). "Conversely, IL-7 receptor (IL7R) and LAMA2, two genes that are upregulated in a number of cancers, were targeted by REST only in the two non-tumorigenic differentiated cell types." (PMID 24922058, 2014). "ROC analysis of laminins in OC sets revealed that LAMA2/A4/A5, LAMB1/B2/B3, and LAMC2 could be used to differentiate between malignant tumors and non-neoplastic tissues." (PMID 34512203, 2021).
myopathy (10 papers, 2011 to 2025). A disease of the muscle in which the muscle fibers do not function properly. "For example, a Japanese patient was diagnosed with mild myopathy and diffuse muscle atrophy at the age of 26, with genetic testing revealing a homozygous mutation in the LAMA2 gene (c.818G>A; p.Arg273Lys)." (PMID 40751275, 2025). "Thus, myopathy resulting from mutations in basement membrane components LAMA2 and COL4A1 might share a common pathogenic mechanism whereby contraction-induced load leads to muscle fiber detachment." (PMID 21625620, 2011). "Lack of improved grip strength and hypertrophy in females as opposed to males is consistent with reports of more severe myopathy in females vs males in other LAMA2-CMD mouse models." (PMID 32498713, 2020). "The observed differences between male and female myopathy and inflammation in LAMA2-CMD remain to be further explored." (PMID 32498713, 2020). "The two most prevalent forms of CMD, i.e., collagen VI (COL6)-related myopathies (COL6RM) and laminin α2 (LAMA2)-deficient CMD type 1A (MDC1A), share a similar underlying disease mechanism, consisting in the deficiency or dysfunction of extracellular matrix (ECM) proteins." (PMID 33138863, 2020).
neuromuscular disease (7 papers, 2017 to 2024). "Mutations in this gene have been associated with LAMA2-related muscular dystrophy (LAMA2-RD), which is a neuromuscular disease characterized by muscle weakness, spinal rigidity and respiratory impairment, as well as by delayed nerve conduction and deceased axon myelination." (PMID 38689650, 2024). "In the present study, we used targeted NGS of 270 neuromuscular disease-associated genes and identified two novel LAMA2 mutations in a Chinese patient with MDC1A." (PMID 29487616, 2018). "Some genetic diseases also lead to a reduced internodal length outcome: Periaxin and Laminin 2 (also called Merosin) mutations induce short myelin sheath internodes in peripheral nerves and lead to CMT4F and Lama2 neuromuscular disease respectively." (PMID 29354031, 2017).
peripheral neuropathy (7 papers, 2015 to 2025). A disorder affecting the peripheral nervous system. "The peripheral neuropathy in LAMA2 MD mouse models is caused by severe defects in axonal sorting and myelination of motor and sensory axons." (PMID 37038437, 2023). "Based on the genotype-phenotype correlations of these three CNVs, we consider LAMA2 to be a new potential target gene for peripheral neuropathy, whereas CNTNAP2 and SEMA5A remain potentially pathogenic." (PMID 25648254, 2015). "Thus, we consider it quite probably that the LAMA2 deletion observed in this patient leads to partial laminin α2 deficiency and is likely causative of the patient's peripheral neuropathy." (PMID 25648254, 2015). "This is accentuated in LAMA2 MD mouse models where the peripheral neuropathy manifests as a progressive hind limb paralysis." (PMID 37038437, 2023). "The peripheral neuropathy manifests as progressive hind limb paralysis and hence strongly contributes to the overall phenotype in LAMA2 MD mouse models." (PMID 37038437, 2023). "In this brief review, we present data supporting the impact of peripheral neuropathy in the LAMA2-RD phenotype, including both mouse models and human studies." (PMID 32390798, 2020). "Peripheral neuropathy is a prominent feature of the disease also in the dyW/dyW mouse model, just like in all mouse models for LAMA2-CMD." (PMID 32457577, 2020). "Next, we tested whether the expression of the two linker proteins would also improve the phenotype (including the peripheral neuropathy) in the most severe mouse model for LAMA2 MD by crossing the CAG-DL triple transgene combination into dy3K/dy3K mice." (PMID 37038437, 2023). "Interestingly, although peripheral neuropathy is pronounced in all LAMA2-CMD mouse models, it is rarely manifested in patients." (PMID 32457577, 2020). "Whether it is an axonal sorting defect that underlies these occasional peripheral neuropathies in human patients remains an open question, largely due to the lack of nerve biopsies from LAMA2 MD patients." (PMID 37038437, 2023). "It is still not clear to which extent peripheral neuropathy contributes to muscle weakness in patients affected by LAMA2-RD." (PMID 32390798, 2020).
infection (3 papers, 2022 to 2025). The state of being infected such as from the introduction of a foreign agent such as serum, vaccine, antigenic substance or organism. "Genes involved in cell adhesion and structural components, including laminins (LAMA2), elastin (ELN), and collagens (COL16A1, COL13A1, COL8A1) were significantly downregulated at 24 hours post-infection (hpi) in both variants." (PMID 41200555, 2025). "Clade I infection was associated with 15 enriched GO terms, driven in part by up-regulation of LAMA1 and LAMA2 (orthologues of Laminin subunit-α)." (PMID 41419766, 2025).
neurological disorder (1 paper, 2020). "Intriguingly these cases suggest that certain LAMA2 mutations can present largely as a neurological disorder, thus expanding the clinical spectrum of MDC1A." (PMID 32792907, 2020).
psychiatric disorder (1 paper, 2023). A disorder characterized by behavioral and/or psychological abnormalities, often accompanied by physical symptoms. "Nevertheless, we detected four inherited rare variants of unknown significance in four respective genes implicated in psychiatric disorders in the patient, including p.Arg1627Trp of LAMA2, p.Arg691Gly of TLR4, p.Pro1338Ser of CSMD1, and Arg182X of AGTR2." (PMID 37511534, 2023).
LAMA2 also shares sentences with these, for which no sentence is quoted: congenital myopathies (4 papers); genetic disease (4); brain malformations (3); polymicrogyria (3); Alzheimer’s dementia (2); amyotrophic lateral sclerosis (2); autosomal recessive disease (2); autosomal recessive limb-girdle muscular dystrophy-23 (2); cardiac failure (2); colon cancer (2); head and neck squamous cell carcinoma (2); Hip dysplasia (2); Intellectual disability (2); laryngeal squamous cell carcinoma (2); nemaline myopathy (2); Onset (2); ovarian carcinoma (2); pneumonia (2); Ullrich congenital muscular dystrophy (2); Adult onset (1); albinism (1); Alzheimer’s disease (1); Anxiety (1); arrhythmogenic right ventricular cardiomyopathy (1); Astigmatism (1); Becker muscular dystrophy (1); beta thalassemia (1); brain tumors (1); Brugada syndrome (1); CADASIL (1).
A further 65 diseases each share a sentence with LAMA2 in 1 paper.